CD4 (CD4 molecule)
Diseases named in the same sentence as CD4 in open-access papers (continued):
Sharing a sentence is not in itself a finding about the gene and the disease.
AIDS (continued). "Each of these animals also met the clinical definition of AIDS as assessed by depletion of CD4+ T cells below approximately 200 cells/μl, indicating that immune suppression may be essential for the development of neuroAIDS." (PMID 28787449, 2017). "Furthermore, interaction analyses showed that HIV-1 subtypes interacted multiplicatively with transmission routes or CD4 count at baseline to contribute to HIV/AIDS progression (P = 0.023 and P < 0.001, respectively)." (PMID 28484257, 2017). "Disseminated Cryptococcus neoformans infection is largely seen in individuals with advanced HIV infection (CD4 < 200 cells/μL); it is an AIDS defining disease accounting for up 15% of AIDS-related death globally and even higher (20–50%) in resource limited settings." (PMID 29371581, 2017). "The subjects under study were in the chronic phase of infection, yet not in advanced stage of the disease (as judged by the abscence of AIDS and the high number of CD4+ T-cell counts), and their proviral quaisispecies population was expected to be fully established." (PMID 29257103, 2017). "Depletion of CD4+ T cells occurs throughout three stages of HIV infection (i.e., acute infection, clinical latency, and acquired immune deficiency syndrome (AIDS)), whereas CD8+ T cells potentially increase in the first stage and remain during the second stage before depleting in the final stage." (PMID 28694558, 2017). "In addition, since lower CD4 count at baseline was a risk factor for fast HIV/AIDS progression, in concordance with the well-known knowledge, we also investigated the interaction of HIV-1 subtypes and CD4 count at baseline." (PMID 28484257, 2017). "Harold Jaffe, who was at the forefront of the discovery of the AIDS epidemic, and his colleagues pointed out that the risks and benefits of treating people with a CD4 count above 350 cells/μL were unknown." (PMID 39450053, 2017). "Since initiating cART at a higher CD4 cell count prevents HIV-associated illnesses, averts new infections, and saves money to achieve the target of ending the AIDS epidemic, current HIV treatment guidelines have evolved to recommend initiating cART regardless of CD4 cell counts." (PMID 28665938, 2017). "On the other hand, of the most commonly used combinations 2NRTI+PI-treated cases presented with the least favourable clinical profile reflected by high percentage of AIDS diagnoses and low baseline/nadir lymphocyte CD4 counts – comparable to nucleoside-sparing PI/r+InI." (PMID 28715160, 2017). "Declining numbers of CD4+ T cells during HIV/SIV infections have long been attributed as the primary cause of immune-deficiency, progression to acquired immune deficiency syndrome (AIDS), and sites of virus reservoirs established during ART." (PMID 29259605, 2017). "However, there is evidence that IL-7 serum concentrations are affected only at very low CD4+ T-cell numbers in AIDS patients, and these levels are far below lymphopenia described in tuberculosis." (PMID 28582466, 2017). "In addition, half of those diagnosed enter care late, defined as presenting to care with CD4 cell count <350 cells/mm3 or an AIDS defining illness within 6 months after HIV diagnosis." (PMID 29084276, 2017). "Two other studies that included patients with no CD4 count restriction from ART start found that low CD8 count predicted AIDS events or all-cause mortality." (PMID 28903507, 2017). "Although WHO guidelines for developing countries with high HIV+/AIDS burden recommend only occasional CD4 count testing, typically for baseline and relapse, the CD4 cell count is frequently measured in low-burden countries to provide closer monitoring and better care." (PMID 29290885, 2017). "Thus, we used clinical data (HIV diagnosis, AIDS diagnosis, treatment start dates, CD4 count and viral load) only to determine the patient's treatment and health status." (PMID 27535219, 2017).
AIDS (continued). "The same could be said of the association of both CD4:CD8 ratio and CD8 count with non-AIDS mortality, although it is possible that associations may only be with specific causes of morbidity and death that we were unable to look at here." (PMID 28903507, 2017). "Since high HCMV viral load levels are significantly associated with death, independently of CD4 counts, other opportunistic infections and highly active antiretroviral therapy (HAARDT) in AIDS patients, Therefore, we choose viral load as indicator of HCMV virulence." (PMID 28467444, 2017). "Finally, CRPA was significantly higher (p = 0.0008) in patients with AIDS, defined as CD4 counts less than 200/μl of blood." (PMID 28331180, 2017). "Given that patients with higher CD4+ cell counts are more likely to be AIDS asymptomatic, such individuals may be less willing or motivated to take cART33–36." (PMID 28600549, 2017). "Two features are believed to be at the core of the scientific consensus on HIV/AIDS: the natural history of the HIV infection (the number of CD4+ cells and HIV RNA copies plotted over the time) and the virus replication cycle (from the virus entry to the virus assembly, budding and maturation)." (PMID 28542584, 2017). "Gender, baseline CD4 count, history of TB co-infection, history of opportunistic infections, and type of ART regimen, were not statistically significantly associated with the time until HIV/AIDS-related death." (PMID 28287498, 2017). "NKG2D+CD4+ T cells are a novel subset of T lymphocytes reported in many AIDs, such as rheumatoid arthritis, Crohn’s disease and granulomatosis with polyangiitis (GPA) (Wegener’s); these cells interact with NKG2D ligand (NKG2DL)-positive cells, such as synoviocytes, endothelial and epithelial cells." (PMID 28455530, 2017). "Among HIV-infected patients with low CD4 counts, talaromycosis is an AIDS-defining diagnosis." (PMID 28260132, 2017). "Inversion of the CD4+/CD8+ ratio was found in all the AIDS patients in our study." (PMID 28035481, 2017). "Patients who start ART at baseline CD4 counts <200 cells/μl have frequently been demonstrated to have a poor immune recovery with increased risk of both AIDS and non-AIDS-related morbidities and mortalities." (PMID 28702270, 2017). "AIDS-related mortality declined with increasing CD4:CD8 ratio and decreasing CD8 count." (PMID 28903507, 2017). "Univariate analysis showed significance differences were observed between the two groups (P < 0.05) in WHO Clinical Stage of HIV/AIDS, CD4 cell count, prior treatment for Tuberculosis (TB) before ART, Hepatitis C Virus (HCV) co-infection or current use of Cotrimoxazole." (PMID 28195204, 2017). "With the decline in AIDS-related events and deaths after the introduction of ART, much attention has been focused on NAEs as main causes of mortality inPLWH, especially in resource-rich settings and in those with higher CD4 cell counts." (PMID 28886092, 2017). "Hence, they presented with late-stage disease (AIDS) and lower CD4 counts, making them prone to infectious complications, resulting in lower Karnofsky performance status and intolerance of chemotherapy-induced toxicities." (PMID 28507339, 2017). "Low CD4/CD8 ratio does not seem to increase the risk of AIDS or death nowadays, which was not true in the earlier cART era." (PMID 27548257, 2016). "However, low CD4/CD8 ratio was the best predictor of non-AIDS cancers (adjusted HR = 2.13 for CD4/CD8 < 0.5; 95% CI = 1.32–3.44)." (PMID 27548257, 2016). "One possible explanation for this is that continuous treatment of HIV+ subjects in the period has determined an increase of CD4+ cell levels with consequent decreasing comorbidity, in agreement with the decrease of non-AIDS morbidity concurrently with CD4+ cell level increase in some HIV+ cohorts." (PMID 27829390, 2016).
AIDS (continued). "The study showed that the CD4 cell count was an independent predictor of AIDS progression, and was also in line with the other research results, which indicated that AIDS progression to death was clustered among patients starting therapy with a CD4 cell count <350 cells/mm3." (PMID 27399071, 2016). "The recent development of consensus definitions of ‘late presentation’ (CD4 below 350 cells/μL or presenting with an AIDS-defining event), ‘presentation with advanced HIV’, and even ‘presentation for care’, and their use going forward, will facilitate comparison between studies in the future." (PMID 27091128, 2016). "Since CD4 cell count levels are used to determine ART eligibility (the criterion was CD4 ≤350 cells/mm3 or an AIDS diagnosis, at the time when the study was conducted), it was estimated that nearly 80% of newly identified, ART-eligible patients in Guangxi were not receiving ART timely." (PMID 27768710, 2016). "It is an acquired immunodeficiency syndrome- (AIDS-) defining disease and occurs with relatively preserved CD4 cell counts." (PMID 27818811, 2016). "Disease progression was modelled as progression through a series of CD4 count categories until AIDS occurred, and the transition rates between these categories were tuned to reproduce the inferred gamma-distributed time to AIDS." (PMID 27815945, 2016). "The mean CD4 count was reported in 19 of 25 studies in HIV/AIDS and ranged from 9 to 100 cells mm3." (PMID 27490100, 2016). "They all reported strong evidence that early initiation of cART significantly reduces the risk of death or AIDS-defining illness irrespective of the CD4+ T lymphocyte count." (PMID 27001753, 2016). "Characteristics of patients—LC group: CD4 ≤350 cells/mm3 or AIDS." (PMID 27348592, 2016). "A better understanding of how pathogen-specific CD4 T cells are infected and/or depleted during HIV infection can provide important clinical insights into host susceptibility to opportunistic infections in AIDS patients." (PMID 27280548, 2016). "Besides this promising anti-tumor function, genome edited CD4+ T cells have been tested as an adoptive cell therapy for HIV/AIDS." (PMID 26527725, 2016). "However, type I IFNs also increase systemic immune activation, a predictor of poor CD4+ T-cell recovery and progression to AIDS, and facilitate production and recruitment of target CD4+ T cells." (PMID 27500281, 2016). "Among people live with HIV/AIDS, low level of CD4 count was a predictor for anemia." (PMID 27070435, 2016). "We did not investigate, whether as a possible consequence of this presentation to care and ART-initiation after presence of AIDS or with low CD4-counts, further clinical outcomes or accelerated death occured in our cohort." (PMID 27927190, 2016). "Sooty mangabeys (SMs) have naturally evolved with SIV to avoid AIDS progression while maintaining healthy peripheral CD4+ T-cell counts and thus represent a model by which therapeutic interventions for AIDS progression might be elucidated." (PMID 27227993, 2016). "The causes of CD4+ T cell depletion in acquired immunodeficiency syndrome (AIDS) patients have not been fully elucidated." (PMID 27145859, 2016). "Moreover, eligibility for antiretroviral therapy for HIV/AIDS and monitoring progression of the disease commonly have been based on the number of CD4+ T lymphocytes in a patient’s venous blood." (PMID 27483008, 2016). "Preliminary review of the Antiretroviral Therapy (ART) registers at Wilkins and Beatrice Road Hospitals, both located in Harare, indicated that 67 and 71 % of patients enrolled into HIV/AIDS care presented late with baseline CD4 of <200 cells/uL and/or WHO stage 3 and 4 respectively." (PMID 27142869, 2016). "Characteristics of patients—VLC group: CD4 count less than 200 or AIDS." (PMID 27348592, 2016).
AIDS (continued). "This last finding is not confirmed by our data in an observational setting, highlighting that LPV/r including regimens resulted the more potent than both ATV/r and DRV/r (even if in this last case not significantly different) in subjects with very low (< = 200/cmm) CD4 counts or AIDS." (PMID 27348592, 2016). "Bystander CD4 T cell death plays a major contribution towards AIDS progression." (PMID 27026376, 2016). "Traditionally KS was considered an AIDS-defining malignancy because the patients who were at highest risk of developing KS were HIV-1 co-infected patients with high HIV-1 viral load and very low peripheral CD4+ T cell counts (<200 cells/mm3), a count that defines patient’s progression into AIDS." (PMID 26913028, 2016). "They demonstrated that Mycobacterium tuberculosis specific-CD4+ T-cells, lost rapidly after HIV-1 infection, express high levels of IL-2 and low levels of MIP-1β contrary to the CMV specific CD4+ T-cells, which possess the reverse profile and typically survive until end stage AIDS." (PMID 26808476, 2016). "The depletion of CD4 T cells is a hallmark of HIV-1 pathogenesis and AIDS progression." (PMID 27026376, 2016). "Median CD4 count was 593 cells/mm3, median nadir CD4 was 190 cells/mm3, and 26 % had prior AIDS." (PMID 26747456, 2016). "In addition, our results underline the importance of accessing information systems with timely CD4 surveillance data to monitor late diagnosis as a critical public health outcome for assessing AIDS prevention and treatment programs in Mexico." (PMID 27027505, 2016). "The CD4 T cell counts and their relation to the prevalence of various etiologic agents in a particular area should be considered before instituting empirical therapy to AIDS patients." (PMID 27795876, 2016). "Non-AIDS mortality was associated with both older age, adjusted HR compared with those aged <60 years 4.35 [95% CI 2.97–6.39], IDU status (3.40 [2.26–5.12]), lower CD4 (2.42 [1.49–3.94]) and prior AIDS diagnosis (1.58 [1.27–1.95])." (PMID 27525413, 2016). "Although universal access to antiretroviral therapy in Latin America has been accomplished in most countries of the region, a large proportion of HIV-infected individuals still present late for care and therefore initiate HAART with low CD4 counts and/or with an AIDS-defining event (ADE)." (PMID 27271083, 2016). "The prevalence of many “non-AIDS” chronic diseases is inversely related to CD4+ cell count." (PMID 27829390, 2016). "The incidence of oral warts increased after ART was initiated, and relative to the early group there was a four-fold increase in oral warts if ART was initiated at a CD4 T cell count less than or equal to 200 cells/mm3 or following diagnosis of an AIDS-defining condition." (PMID 26930571, 2016). "The suboptimal CD4+ T-cell recovery is a clinical concern as immunodiscordant participants show higher mortality rates and increased risk of clinical progression to AIDS-related and non-AIDS-related illnesses." (PMID 27427875, 2016). "Depletion of memory CD4 T cells is a central event in the occurrence of AIDS." (PMID 26640894, 2015). "A total of 980 patients were included, of whom 289 (29.49%), 324 (33.06%), 353 (36.02%), and 387 (39.49%) were defined as AHD according to the definition of a CD4 count <200 cells/μL or AIDS-defining event (ADE) within 1, 3, 6, and 12 months of HIV diagnosis, respectively." (PMID 26356722, 2015). "Mortality among newly diagnosed treatment-eligible HIV cases (with CD4 count ≤ 350 cells/mm3 or missing CD4 but reported as AIDS cases) during the pre-intervention 2010, pre-intervention 2011, post-intervention 2012, and post-intervention 2013 phases, based on Cox model analysis." (PMID 26348214, 2015).
AIDS (continued). "CD4+ cell count is an established prognostic marker for AIDS and death, and current/most recent CD4+ cell count has been shown to be a good predictor of short-term risk of AIDS and death in cohorts comprised of participants in both resource-rich and resource-poor settings." (PMID 25856495, 2015). "Second, CD4+ T-cell count, which is an important diagnostic tool for AIDS, was not available for all patients." (PMID 26413133, 2015). "The two main goals of AIDS treatment are to eliminate viral loads and to raise CD4 + T cell counts." (PMID 26699285, 2015). "However, CD4 cell counts at ART initiation remain below contemporary treatment guidelines, with nearly half (48%) of participants initiating ART in 2012 starting with a baseline CD4 cell count <350 cells/mm3 or an AIDS-defining illness." (PMID 26443752, 2015). "For defining AIDS cancers, there is no doubt that the risk is higher in the case of lower CD4 count (<200 cells/mL)." (PMID 26770197, 2015). "Finally, combinations of both low CD4 cell count and AIDS defining conditions have been also considered late HIV diagnosis." (PMID 26448332, 2015). "Therefore, in order to characterize gut-associated pDCs in HIV/AIDS cases and controls, we probed the respective duodenum biopsies with fluorescently labeled anti-CD303, anti-CD123, anti-CD4, and anti-CD80 monoclonal antibodies." (PMID 26441989, 2015). "PWA who first tested HIV-positive one month before AIDS had a significantly higher proportion of low CD4 count (below 50 cells/mm3), as compared to PWA who first tested HIV-positive seven or more months before AIDS (56.7 % vs. 32.1 %, Chi-square test, p < 0.01)." (PMID 26067992, 2015). "As Nef-containing exosomes are also observed in infected individuals, this could be an important mechanism for large-scale bystander cell death of uninfected CD4 T cells observed in HIV/AIDS patients." (PMID 25961023, 2015). "The destruction of CD4+ T-lymphocytes by HIV is the main cause of the progressive weakening of the immune system in HIV infection, and leads ultimately to acquired immune deficiency syndrome (AIDS)." (PMID 25790185, 2015). "Altogether, the data may provide evidence that shows the value of deworming improved the CD4+ T-cell count and thus delays the spread and the progression of individuals into AIDS." (PMID 26415705, 2015). "As described in other cohorts, morbidity at higher CD4+ counts is dominated by non-AIDS events." (PMID 25856495, 2015). "Data on the relationship of non-AIDS morbidity and latest CD4+ cell counts is more limited." (PMID 25856495, 2015). "Cases were adult people living with HIV/AIDS whose initial CD4 T cell count was < 200/μl of blood." (PMID 26448332, 2015). "Other studies that investigated the incidence and prevalence of ocular diseases among HIV-1-infected patients, such as the Longitudinal Study of the Ocular Complications of AIDS (LSOCA), only enrolled AIDS patients with very low median nadir CD4 count of 30 /μL." (PMID 26375282, 2015). "An accurate and affordable CD4+ T cells count is an essential tool in the fight against HIV/AIDS." (PMID 25622041, 2015). "Death rates and AIDS rates increased sharply the lower the latest CD4+ cell count." (PMID 25856495, 2015). "A low CD4 cell count at NHL diagnosis found to be an independent risk factor for death in pre-cART and early cART eras in two large cohorts, whereas history of AIDS was associated with worse survival only in the pre-cART era." (PMID 25886534, 2015). "While the proportion of patients who had CD4 count > 350 cells/mm3 remained consistent throughout the study (27%), we noted a higher proportion of patients who had CD4 count ≤ 200 cells/mm3 or who were reported as AIDS cases during the pre-intervention phases." (PMID 26348214, 2015).